GBA1 (glucosylceramidase beta 1)
Diseases named in the same sentence as GBA1 in open-access papers (continued):
Sharing a sentence is not in itself a finding about the gene and the disease.
Gaucher disease (continued). "Interestingly, mutations in the GBA1/Gba1 gene that encodes the enzyme acid β-glucosidase has been strongly associated with the development of PD, DLB, and lysosomal storage disease, (e.g., Gaucher disease)." (PMID 35163013, 2022). "Homozygous mutations in the lysosomal glucocerebrosidase gene, GBA1, cause Gaucher’s disease (GD), while heterozygous mutations in GBA1 are a strong risk factor for Parkinson’s disease (PD), whose pathological hallmark is intraneuronal α-synuclein (asyn) aggregates." (PMID 33971917, 2021). "A Gaucher’s disease mouse model expressing mutant GCase showed hippocampal aSyn aggregation and memory deficits, and phenotypes significantly improved by adeno-viral wild-type GBA1 overexpression." (PMID 33381501, 2020). "How to address the counseling of lifetime risk of developing Parkinson’s disease in patients with Gaucher disease and their family members carrying a single variant of the GBA1 gene is not yet clearly defined." (PMID 32967694, 2020). "To date, the relationship between Gaucher disease and α-synucleinopathies such as PD, DLBs, and MSA has been unraveled to some extent such that PD and LBDs patients with GBA1 mutations typically show an earlier onset of the diseases and more severe symptoms than control group." (PMID 29703245, 2018). "Together, our findings indicate that mutations in GBA1 lead to an increased abundance of proteins normally degraded by autophagy, but that the phenotypes accompanying glucocerebrosidase deficiency are largely independent of α-synuclein." (PMID 27019408, 2016). "Importantly, in vivo treatment with a pharmacological chaperon, isofagomine, known to enhance GBA1 function in Gaucher’s disease fibroblasts, suppressed the increased p38 activation and TNF-α formation in brain tissues, and extended life span." (PMID 26312487, 2015). "Although the type of GBA1 mutation plays a role in determining the type of Gaucher disease, it does not fully explain the clinical variability seen among patients." (PMID 24070122, 2013). "Gaucher disease (GD) is an infrequent progressive multisystem lysosomal storage disorder (LSD) caused by the deficient activity of the lysosomal enzyme, glucocerebrosidase (GBA), arising from autosomal recessive mutations in the GBA1 gene (1q21)." (PMID 22247978, 2012). "Using mDA carrying a common mutation in GBA1 intron 2 (a genotype typically associated with Gaucher disease, not the more common heterozygous GBA1 mutations seen in Parkinson's disease), we found 1857 high-confidence pre-mRNA splicing changes from two mutant cell line clones." (PMID 40950074, 2025). "Therefore, to relieve central nervous system (CNS) symptoms related to GBA1 gene abnormality in patients with Gaucher’s disease or PD, gene therapy that delivers GBA1 into the CNS could be an alternative approach." (PMID 39596436, 2024). "Gaucher disease (GD; OMIM #230800), a rare hereditary lysosomal disorder involving lipid accumulation and the malfunction of various organs, is caused by disease-associated variants in glucocerebrosidase (GBA1; also known as GCase), leading to GBA1 protein deficiency in lysosomes." (PMID 38575988, 2024). "Interestingly this variant does not cause Gaucher disease or have a major effect on glucosylceramide levels suggesting a dissociation between glucosylceramide and the role of GBA1 in PD progression." (PMID 38849413, 2024). "Gaucher disease (GD) (Online Mendelian Inheritance in Man (OMIM) 23080, 231000, 231005) is a genetic lysosomal storage disorder caused by the pathogenic variants of the glucocerebrosidase (GBA1) gene and, as a result, a deficiency of the glucocerebrosidase enzyme (GCase)." (PMID 38667330, 2024). "Gaucher disease (GD) [OMIM:231000] is a rare AR subtype of the classical subacute/chronic neuronopathic GD caused by homozygous or compound heterozygous mutations affecting the glucosylceramidase-beta type 1 (GBA1, also known as acid beta-glucosidase) gene on chromosome 1q22." (PMID 37239976, 2023).
Gaucher disease (continued). "In Gaucher disease (GD), a relatively common sphingolipidosis, the mutant lysosomal enzyme acid β-glucocerebrosidase (GCase), encoded by the GBA1 gene, fails to properly hydrolyze the sphingolipid glucosylceramide (GlcCer) in lysosomes, particularly of tissue macrophages." (PMID 38003227, 2023). "Researchers have turned to vertebrate and non-vertebrate models of GBA1-associated parkinsonism to address selected, unresolved topics, such as the specific role of the GCase pathway in Parkinson pathogenesis and to test novel treatments for Gaucher disease." (PMID 31464647, 2019). "Furthermore, the connection between GCase activity and Parkinson disease is complicated by the fact that two mild GBA1 alterations that do not in themselves cause Gaucher disease, E326K (p.E365K) and T369 M (p.T408 M), still predispose patients to parkinsonism." (PMID 31464647, 2019). "Although Ambroxol has been shown to reach the central nervous system and exert a stabilisation effect on GBA1, no randomized studies in large and diverse populations of patients with Gaucher disease have been undertaken." (PMID 39936129, 2025). "In a Gba1-prone mouse model of (Gba1 9V/−) and conduritol B epoxide (CBE)-mediated glucocerebrosidase-targeted experimental mouse model of Gaucher disease, we have shown an increased recruitment of CR3-expressing macrophages and dendritic cells to tissues including the liver, spleen, and lungs." (PMID 39596318, 2024). "Another GBA1 variant in the PPMI study is E365K (N = 24), a PD risk factor that does not cause Gaucher disease in homozygote carriers." (PMID 36854767, 2023). "Glucosylsphingosine is a clinically meaningful biomarker of Gaucher's disease but could not be assayed previously in heterozygous GBA1 carriers." (PMID 34741486, 2022). "It is not uncommon for GBA1 testing to have been done in a prenatal setting in other relatives as part of carrier testing for Gaucher disease, and positive Gaucher results may not be understood to be connected to the risk of developing PD9." (PMID 36446806, 2022). "Genetic approaches and pharmacological approaches demonstrated that GBA1 defects facilitate p38 activation in vitro and in vivo (above); however, whether p38 is highly activated in human Gaucher’s disease is not known." (PMID 26312487, 2015). "Macrocyclic peptide ligands developed via RaPID technology selectively bind and stabilize rhGBA1 in plasma at nanomolar concentrations without inhibiting endogenous GBA1, offering potential for combinatorial ERT-pharmacological chaperone for Gaucher disease." (PMID 39936129, 2025). "These cyclic peptides do not inhibit endogenous GBA1 in cells due to poor cell permeability but can stabilise extracellular rhGBA1 in plasma, presenting significant potential as a combinatorial ERT-pharmacological chaperone therapy for Gaucher disease." (PMID 39936129, 2025).
Parkinson disease (484 papers, 2012 to 2026). "Variants in the LRRK2 and GBA1 genes are among the most common risk factors associated with Parkinson's disease (PD)." (PMID 41786767, 2026). "Parkinson's disease is strongly linked to lysosomal dysfunction, particularly reduced activity of glucocerebrosidase (GCase) encoded by the GBA1 gene." (PMID 42280768, 2026). "Mutations in the GBA1 gene, encoding beta-glucocerebrosidase (GCase), are the most common genetic risk factor for Parkinson's Disease (PD)." (PMID 41957689, 2026). "Lysosomal dysfunction is central to Parkinson's disease pathogenesis, with GBA1 as the strongest established genetic risk factor." (PMID 41757160, 2026). "Our study identified rare GBA1 coding variants to be the most frequent mutations among patients with Parkinson's disease, with a frequency of 4% in our case cohort." (PMID 41058593, 2026). "Such lysosomal impairment is a hallmark of GBA1-associated Parkinson’s disease and is also implicated in sporadic disease, where it drives oxidative stress, perturbs enzyme activity, and promotes α-synuclein aggregation." (PMID 41301891, 2025). "Rare GBA1 variants are the most commonly identified mutations in Parkinson’s disease patients of African and African admixed ancestry, exhibiting a distinct mutation landscape compared to other populations." (PMID 39867380, 2025). "Mutations in GBA1, the gene encodingthe lysosomalhydrolase glucocerebrosidase (GCase), are the strongest common geneticrisk factor for Parkinson’s Disease (PD)." (PMID 41142333, 2025). "The GBA1 gene presented in the heterozygous status is the most common genetic risk factor for Parkinson’s disease (PD)." (PMID 41300721, 2025). "Parkinson’s disease, associated with mutations in the GBA1 gene (GBA1-PD), is the most common genetic form of Parkinson’s disease (PD), marked by clinical heterogeneity influenced by mutation type." (PMID 41009720, 2025). "Indicating a driving role of ALP malfunction – and possibly also of aging – in the pathogenesis of Parkinson’s disease, GBA1 mutation carriers show defects in sphingolipid metabolism and α-synuclein accumulation." (PMID 40399377, 2025). "We identified one candidate causal protein for Parkinson’s disease (GBA1) and two for alcohol use disorder (METAP1 and ADH5) in participants of African ancestry." (PMID 40921788, 2025). "Previous studies showed that mutants with GBA1 deficiency have been associated with neurodegenerative conditions including Parkinson's disease (PD) and dementia with Lewy bodies." (PMID 40465637, 2025). "Yarkova E.S., Grigor’eva E.V., Medvedev S.P., Pavlova S.V., ZakianS.M., Malakhova A.A. IPSC-derived astrocytes contribute toin vitro modeling of Parkinson’s disease caused by the GBA1 N370Smutation." (PMID 40144372, 2025). "More specifically, GBA1 variants in Parkinson disease dopaminergic neurons manifest as hyperactivation of mechanistic target of rapamycin complex (mTORC1), a negative regulator of the lysosome‐autophagy network." (PMID 39822020, 2025). "Heterozygous variants in GBA1 are the commonest genetic risk factor for Parkinson’s disease (PD), but penetrance is incomplete." (PMID 41103722, 2025). "Sidransky syndrome represents a distinct variant of Parkinson’s disease (PD) that is linked to pathogenic variants in the glucocerebrosidase (GBA1) gene." (PMID 40244386, 2025). "Loss of GCase activity in GBA1-Parkinson’s patients has been observed in brain, blood, and cells such as dermal fibroblasts or dopaminergic neurons derived from pluripotent stem cells." (PMID 40399377, 2025). "In a study conducted in Parkinson’s patients linked to GBA1 (β-glucocerebrosidase), a lysosomal hydrolase, it was reported that there was no significant change in RAB7 total protein levels, but TBC1D15 (RAB7-GAP) levels changed." (PMID 40565173, 2025).
Parkinson disease (continued). "When delivering the Parkinson’s disease-associated GBA1 gene, BI-hTFR1 significantly enhanced glucocerebrosidase activity in both brain tissue and cerebrospinal fluid, highlighting its potential for human CNS gene therapy applications." (PMID 40565303, 2025). "Clinical characteristics of Lewy body dementia with GBA1 mutations include younger onset, more frequent and severe parkinsonism, and higher frequency of visual hallucinations and fluctuations." (PMID 41185066, 2025). "More recently, GBA1 mutations have been identified as the most prevalent genetic risk factor for Parkinson’s disease (PD), associated with more pronounced symptoms characterized by earlier onset and accelerated cognitive decline." (PMID 40333681, 2025). "In 2009, a multicenter international collaborative study conclusively established the connection between GBA1 mutations and Parkinson’s disease (PD) highlighting GBA1 variants as common genetic risk factors for the development of PD." (PMID 38251062, 2024). "One of the remarkable findings of recent years is the relationship between the heterozygous variants of the GBA1 gene and a 4%–9% increase in the probability of developing Parkinson's disease." (PMID 39463025, 2024). "For instance, AAV-GBA1, designed to address GBA1 mutations in type II Gaucher disease, can also be repurposed to target Parkinson’s disease, given that GBA-1 mutations represent a common genetic risk factor for both conditions." (PMID 39559557, 2024). "We performed directed differentiation of nine iPSC lines: three lines from a Parkinson’s disease patient carrying the N370S GBA1 mutation, 3 iPSC lines from an asymptomatic carrier of the mutation, and three iPSC lines from healthy donors." (PMID 38672099, 2024). "The most common genetic risk factors for Parkinson’s disease are GBA1 mutations, encoding the lysosomal enzyme glucocerebrosidase." (PMID 37748026, 2024). "Here we present the first comprehensive study of Hungarian patients with GBA1-associated Parkinson’s disease." (PMID 38153678, 2024). "Further research should focus on understanding placental transfer mechanisms to enhance the accuracy of lyso-Gb1 assessments, particularly in the context of GBA1-associated Parkinson’s disease." (PMID 39596090, 2024). "One of the most common genetic risk factors for Parkinson’s disease (PD) are variants in GBA1, which encodes the lysosomal enzyme glucocerebrosidase (GCase)." (PMID 38883744, 2024). "Our observations are especially important regarding the level of lyso-Gb1 in GBA1-associated Parkinson’s disease (GBA1-PD), and the fact that an increased risk of developing PD has been observed in both GD patients and carriers." (PMID 39596090, 2024). "GD has been linked to other neurodegenerative diseases such as Parkinson’s disease (PD); mutations in the GBA1 gene have been identified as a common risk factor in many PD patients." (PMID 38757200, 2024). "The most common heterozygous variants of the GBA1 gene are c.1226A>G (N370S, rs76763715) and c.1448T>C (L444P, rs421016), which are associated with an increased risk of Parkinson’s disease." (PMID 38672099, 2024). "Mutations in the GBA1 gene, which encodes the lysosomal enzyme glucocerebrosidase (GCase), are associated with Gaucher disease and increased risk of Parkinson’s disease." (PMID 39795868, 2024). "Loss-of-function variants in the GBA1 gene are also the most common genetic risk factor for Parkinson’s disease (PD) and dementia with Lewy bodies (DLB)." (PMID 38329128, 2024). "Mutations in the glucocerebrosidase 1 (GBA1) gene, encoding β‐glucocerebrosidase (GCase), are the most common genetic risk factor for Parkinson's disease (PD) and other synucleinopathies." (PMID 38641924, 2024). "Mutations in the GBA1 gene are one of the most common risk factors for Parkinson’s disease (PD) besides SNCA, LRRK2, and MAPT." (PMID 38203854, 2024).
Parkinson disease (continued). "Since GBA1 is a known risk gene for both Parkinson’s disease and dementia with Lewy bodies, our analysis shows that variation in GBA1 does not distinguish between LBD-D and LBD-ND within a study of this size." (PMID 38978726, 2024). "In cell models of Parkinson’s disease caused by the p.N370S mutation in the GBA1 gene, it has been shown that ER stress can actively manifest and cause dysfunction in patient-specific neurons." (PMID 38672099, 2024). "GBA1 mutations increase the risk of Parkinson’s disease, and Parkinson’s patients exhibit decreased β-glucocerebrosidase activity." (PMID 38256144, 2024). "GBA1-associated Parkinson’s disease (GBA1-PD) is increasingly recognized as a distinct entity within the spectrum of parkinsonian disorders." (PMID 39000225, 2024). "GBA1 variants were relatively common (15%) in our Hungarian Parkinson’s disease cohort, with the E365K and T408M variants being the most frequent." (PMID 38153678, 2024). "Of note, mutations in GBA1 are associated with Parkinson disease (PD) in adults, and ambroxol has been effectively used for these patients." (PMID 38553911, 2024). "In cell models of Parkinson’s disease, specifically those caused by the p.N370S variant in the GBA1 gene, ER stress has been shown to actively manifest and cause dysfunction of patient-specific neurons." (PMID 38672099, 2024). "The G-Can (GBA1-Canada) Initiative, an open-science collaborative initiative aimed at addressing GBA1 mutation based Parkinson’s disease, has made contributions to this research." (PMID 38883744, 2024). "Mutations in the GBA1 gene have been identified as a prevalent genetic risk factor for Parkinson’s disease (PD)." (PMID 37745332, 2024). "As a model to study ER stress, we chose DA neurons derived from iPSC of a Parkinson’s disease patient and an asymptomatic carrier of the N370S mutation in the GBA1 gene." (PMID 38672099, 2024). "In the GBA1 gene, the functional polymorphism E326K (rs2230288), which associates with an increased risk of Parkinson’s disease and Lewy body dementia, decreases glucocerebrosidase activity in vitro." (PMID 36771351, 2023). "This has led researchers to discover that mutations in GBA1 are a genetic risk factor for synucleinopathies similar to Parkinson’s disease (PD) and DLB." (PMID 37304077, 2023). "Genetic variants in GBA1 and LRRK2 genes are the commonest genetic risk factor for Parkinson disease (PD); however, the preclinical profile of GBA1 and LRRK2 variant carriers who will develop PD is unclear." (PMID 36881256, 2023). "Intravenous administration of the same vector (AAV9-GBA1) is being investigated in 24 Parkinson’s patients with a mutation in the GBA1 gene (NCT04127578)." (PMID 36835039, 2023). "PD-related mutations in LRRK2 and GBA1 slow the degradation of alpha-synuclein, thus directly implicating the dysfunction of the process in the neuropathology of Parkinson’s disease." (PMID 36085537, 2023). "This study provides the first measurement of DNA methylation of α-synuclein in individuals with Parkinson’s disease who carry GBA1 mutations." (PMID 36769009, 2023). "Nevertheless, models have provided evidence that Parkinson’s disease-associated mutations in GBA1 are connected to synaptic dysfunction." (PMID 36864664, 2023). "An example is GBA1-associated parkinsonism, which is typically associated with a relatively younger age at onset." (PMID 37980685, 2023). "Glucosylceramidase beta 1 (GBA1) is a representative example that has been reported to be the etiological factor for Parkinson’s disease (PD), which results from heterozygous mutation of this gene, now categorized as GBA-PD35." (PMID 37258585, 2023). "Patients with type 1 GD and carriers of GBA1 mutations have a higher propensity to develop Parkinson's disease." (PMID 36835356, 2023).